TNF (tumor necrosis factor)
Diseases named in the same sentence as TNF in open-access papers (continued):
Sharing a sentence is not in itself a finding about the gene and the disease.
infection (continued). "Nevertheless, YH supplementation decreased the concentrations of TNF-α and IL-1β in LPS-challenged piglets, which indicated dietary YH supplementation could decrease the systemic inflammation after LPS infection." (PMID 36932457, 2023). "Infections due to human respiratory syncytial virus (HRSV) and human bocavirus (HBoV) can mediate the release of several pro-inflammatory cytokines such as IL-6, IL-8, and TNF-α, which are usually associated with disease severity in children." (PMID 37239461, 2023). "With respect to infections, in addition to surveillance for TB prior to initiation of TNF-targeted therapy, vigilance for infectious complications should be maintained during the therapy course, since there is a known increased risk of opportunistic infections, mostly mild forms." (PMID 37835065, 2023). "TNF is essential for anti-fungal immunity, activating macrophages and neutrophils to kill Candida and stimulating the recruitment and extravasation of immune cells to the site of infection." (PMID 38003833, 2023). "At 3 days post-infection, intravenous administration of hMSCs significantly decreased the concentrations of pro-inflammatory cytokines and chemokines, i.e. TNF-α, IL-1β, MCP-1, CXCL1 in lung homogenate and/or BAL fluid, respectively, as compared with mice treated with NHLFs group." (PMID 37704783, 2023). "As we noticed a difference in early TNF-α and IL-6 production after infection with the two strains, we examined whether PPAR-γ activation could play a role in the expression of these cytokines." (PMID 37376550, 2023). "Therefore, we sought to dissect the role of TNF and the differential contributions of TNFR1 and TNFR2 in protection against S. aureus skin by comparing mice deficient in TNF, TNFR1, and TNFR2 in a S. aureus intradermal infection mouse model." (PMID 37327341, 2023). "Moreover, CRP plays a crucial role in response to the host’s infection through NO release, phagocytosis, apoptosis and cytokine production, particularly IL-6 and TNF-α." (PMID 37237892, 2023). "Moreover, TNF treatment of astrocytes before infection upregulates TNFR1 expression, reinforcing the need for two signals to enhance TNFR1 expression." (PMID 37018799, 2023). "The absolute levels of TNF-α, IL-1β and IL-6 in P815 cells measured by ELISA confirmed the results from gene expression with RNA-seq analysis; thus, melatonin significantly reduced inflammatory cytokine levels at 12 h post-infection." (PMID 37200384, 2023). "F4/80 is a cell surface molecule which is highly expressed on murine monocytes and tissue macrophages, whereas TNFα is a proinflammatory cytokine which is known to be highly produced by macrophages during inflammation, injury or infection and thus mainly indicates pro-inflammatory M1 macrophages." (PMID 37435490, 2023). "Notably, infection with ZIKVMR766 has been associated with higher rates of animal death, increased virus replication, and elevated levels of TNF-α, IL-6, and IL-1β in the brain." (PMID 37376550, 2023). "VEGFA and ELR + chemokines appear to be induced by TNF and play a role in infection dissemination." (PMID 38036985, 2023). "Increased levels of IFN-ɣ and TNF-α were reported during infection (visit 1) in both groups." (PMID 36975498, 2023). "At 24 h post-infection, the TNF signaling pathway and MAPK signaling pathway were enriched." (PMID 37515115, 2023). "Besides the positive effects of MCs in fighting infections, on the other hand, viruses stimulate mucosa MCs to release pro-inflammatory cytokines such as IL-1, TNF, IL-6, and proteases which aggravate the inflammatory state." (PMID 37515272, 2023). "Using xylose-deficient mutants, researchers found that these cryptococcal cells lacking xylose had increased T-cell recruitment in murine models of infection which was driven by an increased pro-inflammatory response (IL-1β, IL-6, TNF-α, and IL-12p40) from cDC2 cells." (PMID 37998856, 2023).
infection (continued). "In addition to their direct antimicrobial functions, neutrophils can release proinflammatory cytokines, including TNF-α and IL-1β, which promote local inflammation and recruit other immune cells to the site of infection." (PMID 37895050, 2023). "Interestingly, even if anti-TNFα therapy was used only for the first two weeks of the infection, mice were still unable to control the infection and succumbed in a time frame similar to those receiving continuous anti-TNFα therapy." (PMID 37233265, 2023). "Chicks' immune systems are significantly activated by infection with Salmonella Enteritidis, resulting in an acute immunological emergency and excessive production of pro-inflammatory factors, including IL-1β, IL-6, and TNF-α." (PMID 37990191, 2023). "However, similar to the present work, AMs from young horses had higher TNF-α gene expression and lower IL-10 expression than MDMs after infection with virulent Rhodococcus equi." (PMID 36920969, 2023). "To address whether inflammation-mediated activation of BBB endothelial cells is a prerequisite for infection by SARS-CoV-2, we stimulated EECM-BMEC with the pro-inflammatory cytokines TNFα/IFNγ prior to infection." (PMID 37875964, 2023). "TNF-α can inhibit the growth of certain tumors, which acts as an immune modulator and a mediator of the inflammatory response and also plays a key role in the body’s resistance to infection." (PMID 37370417, 2023). "The rapid production of iNOS and TNFα is crucial for the host to effectively control the infection." (PMID 37836523, 2023). "In M. abscessus, ESX-3 induces pro-inflammatory cytokines like TNF-α, IL-6, IL-1β, and IL-12p40 in murine and human macrophages and is associated with activation of mitogen-activated protein kinase (MAPK) as well as NF-κB signaling after infection." (PMID 37200238, 2023). "IL-17 and TNF-α could regulate chemokine expression and modulate immune cell recruitment, including T cells, in the site of infection." (PMID 37686061, 2023). "After injury or infection of a wound, immune cells, particularly resident macrophages (Mφ), are triggered by pro-inflammatory mediators IL-1α, IL-1β, IL-6, tumor necrosis factor-α (TNFα), cyclooxygenase-2 (COX-2) and phospho-p65, which trigger transcription factor NF-κB." (PMID 36901790, 2023). "CRP, synthesized primarily by the liver in response to inflammatory cytokines (interleukin-6, interleukin-8, and tumor necrosis factor-α), is one of the most frequently used inflammatory markers in clinical practice and is released following either an infection, inflammation, or tissue damage." (PMID 37286951, 2023). "Importantly, the levels of TNFα mRNA at 24 and 96 h post-infection were significantly higher in infected human macrophages kept under hypoxia." (PMID 36793725, 2023). "Therefore, TNF α inhibitors are expected to have some influence on the rate of surgical site infection (SSI) in RA patients." (PMID 38013343, 2023). "TNF-α and IL-1β are known to initiate innate immune response, and mediate the activation, recruitment, and adherence of circulating macrophages and neutrophils to the infection site." (PMID 38053527, 2023). "As inflammatory cytokines (IL-1, IL-6, IL-8, TNF-α) are induced by the infection of CF lungs, additional studies, e.g., bulk RNA sequencing, may reveal new inflammatory pathways that are upregulated by P. aeruginosa during prolonged infection of HBE." (PMID 37998353, 2023). "Of note, although individuals with COVID-19 infection prior to the 1st vaccination were excluded from this study, we had reported that such individuals showed increased transient IFN-γ, IP-10/CXCL10, TNF-α, and IL-6 responses compared to infection-naïve persons, but only after the 1st vaccination." (PMID 38090597, 2023). "T helper 1 (Th1) cell cytokines, such as IFN-γ and TNF-α are considered inflammatory mediator in the brain following infection or injury, while Th2 cytokines (IL-4, IL-5, IL-13, etc.)and IL-10 may modulate Th1 proinflammatory responses." (PMID 37426673, 2023).
infection (continued). "This correlation could suggest a coordinated immune response to combat the infection, where TNFα acts as a trigger for NK cell activation." (PMID 38137381, 2023). "Similarly, a study by Wei Chen and his colleagues found that the expression of TLR7, MyD88, TRAF6 and TNF-α was significantly increased in mice orally administered B. breve CCFM1026 after FM1 infection." (PMID 37928517, 2023). "The co-infected condition showed the major immune activation effect early (24h) post-infection with 238 immunological pathways uniquely enriched, including IFN-γ and TNF production, while 182 shared pathways were overlapping at 96h post-infection among different conditions." (PMID 37662901, 2023). "In examination of mice deficient in CD8 effector functions, infection of IFNγ deficient (Ifng−/−) and perforin deficient (Prf−/−) mice but not TNFα deficient (Tnfa−/−) mice resulted in worsened disease." (PMID 37866114, 2023). "Furthermore, these two PRRSV strains elicited divergent cytokine responses, such that SD53-1603 infection induced higher levels of TNF-α and IFN-γ, whereas HuN4 infection upregulated IL-1β." (PMID 37920268, 2023). "As the first line of defense of the lung, the airway epithelium provides a physical barrier to prevent infection but also produces chemokines and cytokines such as TNF-α, IL-1β, IL-6, IL-8, and IL-12 that are important mediators in both lung defense and inflammation." (PMID 38102682, 2023). "Moreover, the results displayed that increasing TQN levels significantly (p < 0.05) decreased the expression levels of IL-8, TNF-α, IL-6 and IL-1β genes un like the control group at 96 h post-infection with P. multocida." (PMID 38292130, 2023). "Indeed, using a fluorogenic substrate assay to interrogate downstream caspase-3/7 enzymatic activity during infection, we found that TNF-licensed cells demonstrated significantly lower caspase-3 and -7 activity relative to unprimed cells." (PMID 37279255, 2023). "Interestingly, the frequencies of IFNγ and TNF-producing NP-specific T cells in the BAL were superior to the ones observed after natural infection, confirming the potent adjuvant effect of IL-1β on local TRM formation in pigs." (PMID 37153548, 2023). "In the early stages of infection, TNF-α and IL-6 can activate neutrophils, and the more rapid lytic activity of lysins may lead to more peptidoglycan fragments, which provoke severe proinflammatory reactions." (PMID 37125939, 2023). "Moreover, IL-1β (p = 0.014) and TNF-α (p = 0.001) cytokines were significantly upregulated by the infection, which was reduced (p < 0.05) by zingerone." (PMID 37626627, 2023). "However, our study found that IBD patients on anti-TNF therapy who had a breakthrough infection after a third vaccination had significantly higher anti-S-IgG levels compared to uninfected patients on anti-TNF therapy." (PMID 37766088, 2023). "Furthermore, the levels of viral load, IFN-dependent and inflammatory cytokines (IFN-β, IFN-γ, TNF-α, and IL-6) mRNA were assessed in the brain tissue of mice at 7 days post infection, also revealing a diminished pathogenicity of GETV-K648A and GETV-R649A." (PMID 38110975, 2023). "We found that the levels of TNFα, IL-6, and IFNγ were comparable in control and butyrate-treated mice 18 hours post-infection, suggesting that butyrate did not dampen pro-inflammatory cytokine production in the airways during infection." (PMID 37178819, 2023). "During an infection caused by Gram-negative bacteria, the synthesis of proinflammatory cytokines such as TNF-α and IL-1, IL-6, IL-8, and IL-10 is also more frequent." (PMID 37762882, 2023). "Furthermore, there is an interesting indication from animal studies that andrographolide can reduce inflammation (measured by IL-6 and TNF-α), whilst keeping sufficient inflammatory activity to fight off an infection." (PMID 37765014, 2023).
infection (continued). "Cytokines (e.g., TNF, IL-1β, IL-6, interleukin-17 (IL-17)) from macrophages, mast cells, and other immune cells interact with sensory neurons through these cytokine receptors during infection/inflammation, allergy, and tissue damage/injuries." (PMID 37767094, 2023). "Infection with pathogens can trigger varied levels of TNF-α expression." (PMID 38129415, 2023). "The infection of cells with this bacterium blocks TNF-induced apoptosis." (PMID 38112844, 2023). "Notably, the recombinant virus reduced anti-inflammatory and pro-inflammatory responses by regulating IFN-γ, TNF-α, and IL-1β secretion after infection." (PMID 37741960, 2023). "Infection with some HPV types (i.e., high-risk HPV-35, -39, and -68) was associated with higher cervicovaginal cytokine concentrations, particularly of IL-17A, IL-17F, TNF-α, IL-25 and IFN-γ." (PMID 36992467, 2023). "Furthermore, the infection also encourages macrophages to secrete pro- and anti-inflammatory cytokines such as tumor necrosis factor-α (TNF-α), interleukin-1β (IL-1β), IL-6, interferon-γ (IFN-γ) and IL-10." (PMID 37280772, 2023). "The use of anti‐TNF drugs in AS patients who were infected with COVID‐19 was associated with a mild form of infection, without the need for hospitalization." (PMID 37382255, 2023). "T may prevent and control infection of the host by bacteria by increasing expression of E-selectin (induced by TNF-α) and vascular adhesion molecule-1 in endotheliocyte, which are paramount in trans-endothelial migration of phagocytic cells." (PMID 36864844, 2023). "Increased levels of TNF were also detected after intranasal administration with either virulent BoHV-1 (IBRV strain HB06) or its attenuated deleted mutants (BoHV-1 gG−/tk−, BoHV-1 gE−/tk−): however, higher TNF levels were detected after infection with the wild-type strain." (PMID 37112697, 2023). "Indeed, we observed a significant decrease in TNF-licensed cell death early during infection, as well as significant attenuation of both IL-1α and IL-1β release, in Casp11-/- BMDMs relative to wild-type controls." (PMID 37279255, 2023). "However, another study found that 18 days after infection, there is a significant increase in TNF-α and IL-10 levels in infected dogs, but this difference disappears after 30 days." (PMID 37627021, 2023). "Our results indicated that EBV might modulate antigen expression in the presence of TNF-α and influence peripheral cytokine expression differently in each stage of infection." (PMID 37896882, 2023). "Hence, the pooled analysis of CRP and TNF-α was conducted utilizing the random effect model, whereas the pooled analysis of infection-related complications was carried out through the use of the fixed-effect model." (PMID 37566134, 2023). "In addition, the interpretation of the results can be further complicated due to the dual function of TNF-α, as a pro-inflammatory factor in the initial infection and as an anti-inflammatory or immunoregulatory factor in the later phases of the response." (PMID 37510392, 2023). "The apparent drop in CD8+ IFNγ and TNF responses to Delta peptides compared with ancestral peptides among cases was particularly striking and suggests a role for cross-reactive CD8+ T cells in protection against infection with the Delta variant." (PMID 37655880, 2023). "In addition, expression of MMP-7 or MMP-3 in the liver or small intestine, respectively, increased upon infection, and this was suppressed by anti-TNF-α Ab treatment." (PMID 37939119, 2023). "There is evidence that HIV may increase bone turnover by itself and that it may be associated to an increase in cytokine expression, such as IL-6 and TNF during infection." (PMID 37753486, 2023). "Overall, infection by ΔPdh resulted in a 5-fold increase in the IL-10/TNFα ratio." (PMID 37384800, 2023). "The 2308ΔeryA infection induced similar levels of IL-6 and TNF-α to 2308 infection." (PMID 37671873, 2023).
infection (continued). "However, infection markedly increased the expression of inflammatory cytokines (IL-6 and TNF-α) and the apoptotic genes (Caspase-3 and BCL2)." (PMID 36875142, 2023). "At 8 h and 12 h post-infection, the levels of TNF-α, IL-6, and MCP-1 in both primary astrocytes and BV2 cells infected with the two S. parasuis strains were significantly higher than those of cells infected with S. suis strain P1/7, except for the MCP-1 in primary astrocytes at 12 h post-infection." (PMID 37111486, 2023). "Notably, we observed that, within the first 8 hours of infection, TNF-licensed cell death as measured by PI uptake and LDH release depended on caspases-1 and -11." (PMID 37279255, 2023). "TNFα can induce either NF-kB-mediated survival or apoptosis, while IL-1β is a potent pro-inflammatory cytokine that plays a critical role in the host’s defense responses to infection and injury." (PMID 37998029, 2023). "We found that long-term infection of M. hyorhinis induced the secretion of TNF-α." (PMID 37867861, 2023). "In this analysis, it would be highly interesting to incorporate additional inflammatory markers such as TNF alpha, Interleukin-1, and Procalcitonin as well as clinical parameters such as duration of hospital stay, incidence of surgical site infection, and postoperative bleeding." (PMID 37571352, 2023). "Similarly, in gp91-/- mice, A. nidulans induced significantly more TNF-α than A. fumigatus (p<0.01 at d3 and p<0.0001 at d7 post-infection)." (PMID 37724291, 2023). "We next sought to determine how TNF may be enhancing caspase-11 inflammasome activation during infection." (PMID 37279255, 2023). "In addition, A. nidulans infection induced significantly more TNF-α than A. fumigatus at d3 and d7 post-infection (p<0.0001 and p<0.05 respectively) in WT mice." (PMID 37724291, 2023). "Early in infection, the infected cells are activated and start to release some early mediators of inflammation such as TNF-α, IL-1α, IL-1β, IFN-γ and chemo-attractant molecules (e.g. CXCL5, CXCL8), some of which also characterize the early stages of SARS-CoV-2 infection." (PMID 37662901, 2023). "By contrast, cells that were pretreated with chloroquine before infection exhibited trends towards decreasing levels of proinflammatory TNF-α, IL-6 and IFN-γ, and increasing levels of IL-1β, compared with untreated cells infected with Mel+ or Mel˗ S. globosa conidia." (PMID 37141335, 2023). "There was a non-significant trend towards less seropositivity in the anti-TNF group for patients with an infection more than six months before sample collection (10/19 52.6%) compared to an infection in the six months before sample collection (13/19 68.4%; p = 0.51)." (PMID 37198536, 2023). "In addition, KYNA decreased TNF and nitric oxide levels in the serum of mice treated with LPS, and increased survival rates after LPS infection." (PMID 37235428, 2023). "All clinical data indicate infection is resolved, while increased TNF-α may reflect altered proportions of peripheral T-cells as a hangover of infection." (PMID 37427401, 2023). "In addition to patient choice, interruption of anti-TNFα agents is often recommended at times of intercurrent infection or before elective surgical procedures." (PMID 38124137, 2023). "TNF is the main regulator of cell survival, apoptosis, and necroptosis, and the study of TNF signaling is an important pathway for recognizing necroptosis because it plays an important role in the inflammatory response induced by infection or injury." (PMID 36845112, 2023). "Thus, there was an alteration of the natural course of the infection by the use of anti-TNF immunosuppressant, leading to a delay in the spleen dysfunction." (PMID 38106411, 2023). "In the present study, we found that the immune response in the intestine of rats in the IEC group heightened by expressing more product of TNF-α and IL-1β when encountering the secondary infection of S.Typhimurium, which was consistent with previous studies about trained immunity." (PMID 37090706, 2023).